ACAT1 (acetyl-CoA acetyltransferase 1)
Diseases named in the same sentence as ACAT1 in open-access papers (continued):
Sharing a sentence is not in itself a finding about the gene and the disease.
oral squamous cell carcinoma (1 paper, 2023). "However, the expression of ACAT1 and its prognostic value in oral squamous cell carcinoma (OSCC) has remained unexplored." (PMID 36816175, 2023).
osteoarthritis (1 paper, 2025). A noninflammatory degenerative joint disease occurring chiefly in older persons, characterized by degeneration of the articular cartilage, hypertrophy of bone at the margins and changes in the synovial membrane. "Collectively, these findings suggest that ACAT1 may serve as a potential risk factor in osteoarthritis." (PMID 40164659, 2025). "However, our current study reveals an up-regulation of ACAT1 expression in the synovium of patients with osteoarthritis, and a negative correlation with the levels of TGFB2 and IL-3." (PMID 40164659, 2025).
ovarian tumor (1 paper, 2022). "In contrast to our observations in plasma, but similar to our results in ovarian tumor tissue, ACAT1 protein levels from peritoneal fluid were significantly higher in women with EOC and very low in both normal and BPM cohorts." (PMID 35399074, 2022).
Parkinson disease (1 paper, 2018). A progressive degenerative disorder of the central nervous system characterized by loss of dopamine producing neurons in the substantia nigra and the presence of Lewy bodies in the substantia nigra and locus coeruleus. "Given the pivotal role of the SOAT1/ACAT1 gene in cholesterol esterification as well as its important role in the progression of neurodegenerative diseases, such as AD and Parkinson’s disease, RNA and protein measurement validation experiments were focused on SOAT1/ACAT1." (PMID 30390000, 2018).
pneumonia (1 paper, 2022). An acute, acute and chronic, or chronic inflammation focally or diffusely affecting the lung parenchyma, caused by an infection in one or both of the lungs (by bacteria, viruses, fungi, or mycoplasma.). "Among the 46 metabolic pathways-related proteins (28 up-regulated and 18 down-regulated), alpha-enolase (ENO1), neutrophil gelatinase-associated lipocalin (LCN2), and Acetyl-CoA acetyltransferase (ACAT1) have been found to be related to pathogens-induced pneumonia." (PMID 36387401, 2022).
prostatitis (1 paper, 2025). An infectious or non-infectious inflammatory process affecting the prostate gland. "We revealed two Tier 2 genes (NOA1 and ELAC2) and one Tier 3 gene (ACAT1) for BPH, two Tier 3 genes (TRMU and SFXN5) for prostatitis, and six Tier 3 genes (MRPL24, NDUFS6, PUS1, NBR1, GLOD4, and PCBD2) for PCa." (PMID 40919435, 2025).
renal fibrosis (1 paper, 2021). A final common manifestation of a wide variety of chronic kidney diseases characterized by glomerulosclerosis and tubulointerstitial fibrosis. "Based on the analysis of specific genes expressed in cisplatin-induced renal fibrosis, ACAT1, GGT1, and PDK2 were predominantly expressed in tubule cells." (PMID 34777334, 2021). "Indeed, upregulated expression of ACAT1 was found during renal fibrosis by participating in the oxidation of fatty acids." (PMID 34777334, 2021).
rheumatoid nodule (1 paper, 2022). "Staining for ACAT1 and ABCA1 in the rheumatic mitral valve was positive beside the rheumatoid nodule." (PMID 36307855, 2022).
Sepsis (1 paper, 2021). Sepsis is defined as life-threatening organ dysfunction caused by a dysregulated host response to infection. "In septic mice, 3HB caused an elevation in Nceh1 expression in skeletal muscle, compared to both placebo-treated septic mice and healthy mice, whereas expression of the main enzyme for cholesterol esterification, Acat1, was unaffected by sepsis and 3HB." (PMID 34274000, 2021).
ZIKV infection (1 paper, 2022). "DGAT1, ACAT1, AGPAT1, and AGPAT2 mRNA levels were increased after ZIKV infection (albeit < 1.5-fold compared with the levels in the mock control), indicating that ZIKV infection promotes LD biosynthesis." (PMID 36405969, 2022). "Although the expression of the DGAT1, ACAT1, AGPAT2, and AGPAT1 genes, which are involved in LD biosynthesis, was activated, fatty-acid synthases (SCD1 and FASN, but not ACC1) were significantly downregulated during ZIKV infection." (PMID 36405969, 2022).
tumor (145 papers, 1983 to 2025). "Their data convincingly showed that the loss of ACAT1 in tumor cells promoted B cell viability and TLS formation." (PMID 40166937, 2025). "GSVA was employed to process the data obtained from the TCGA database using R software, revealing a positive association between ACAT1 and tumor proliferation." (PMID 38817856, 2024). "While ACAT2 has limited value in tumors, ACAT1 has been found to be implicated in tumor occurrence and development." (PMID 38720812, 2024). "ACAT1 activity in association with SCOT secures the vital ketolytic supply to tumor cells by pulling in the influx of BHB." (PMID 36836124, 2023). "The high expression of ACAT1 in tumor-associated immune cells can reduce the level of intracellular free cholesterol and promote the composition and function of the membrane." (PMID 37064872, 2023). "Possible correlations of ACAT1/CE levels between plasma, peritoneal fluid and ovarian/tumor tissue were also assessed to evaluate their diagnostic potential." (PMID 35399074, 2022). "In the present study, we investigated the abnormal expression of ACAT1 in NPC, revealing a role for ACAT1 in the biological behavior of this tumor, and related to the underlying molecular mechanisms associated with altered ketone body metabolism." (PMID 34485115, 2021). "The network associated with regulation of tissue invasion by tumor cell lines and lipid export was connected by five proteins: ACAT1, CAV1, CTSS, S100A12, and S100A9." (PMID 33607292, 2020). "Their experiments were done in a mouse model and showed strongly enhanced anti-tumor activity of mouse CD8+ effector T cells treated with avasimibe or deficient for ACAT1." (PMID 31681760, 2019). "Compelling evidence has implicated ACAT1 inhibitor in the inhibition of the growth and development of various tumor cells." (PMID 29793481, 2018). "Furthermore, the adoptive transfer of ACAT1‐deficient CD8+ T cells into tumor‐bearing mice significantly delays tumor growth and improves the survival rate of the host mice." (PMID 40223597, 2025). "Notably, ACAT1 expression was positively associated with overall survival, especially when the abundance of tumor-infiltrating NK cells was high, suggesting that ACAT1 is beneficial for NK cell immunity in CRC." (PMID 40289129, 2025). "First, since ACAT1 is an enzyme located in mitochondria, differences in the number of mitochondria or deficient mitochondria in some OSCC tumours could potentially affect ACAT1 expression." (PMID 36816175, 2023). "Mice that received this combined treatment exhibited significantly longer survival and smaller tumor sizes (P< 0.01), suggesting that the ACAT1 inhibitor enhances the effect of the CSCs-DC vaccine against postoperative tumor recurrence." (PMID 40491907, 2025). "In contrast, USP19 stabilizes ACAT1 by removing ubiquitin chains, enhancing cholesterol esterification and supporting tumor growth, as observed in hepatocellular carcinoma." (PMID 40370434, 2025). "As expected, ACAT1 depletion resulted in decreased tumor angiogenesis, as detected by decreased endothelial cell proliferation, migration and tube formation." (PMID 41184227, 2025). "More recently, two studies from Youjun Li’s group suggest that ACAT1-mediated acetylation promotes tumor growth by regulating tumor cell lipid metabolism in preclinical models of colorectal cancer and hepatocellular carcinoma." (PMID 40166937, 2025). "Our research demonstrated that TRIM59 facilitates ACAT1 ubiquitination in pRCC, thereby reducing endocytic phospholipid synthesis and inhibiting mitochondria-dependent apoptosis, ultimately promoting tumor growth." (PMID 40790033, 2025). "Of note, the tumor growth of mice treated with anti-asialo-GM1 antibody demonstrated that the antitumor effect of ACAT1 was dependent on NK cells." (PMID 40289129, 2025). "Taken together, these results suggest that ACAT1 pS60 facilitates activated NK cells to impair tumor growth." (PMID 40289129, 2025).
tumor (continued). "Taken together, these findings demonstrate that ACAT1 pS60 enhances the abundance of tumor-infiltrating cytotoxic NK cells via p50 K146ac to inhibit tumor growth." (PMID 40289129, 2025). "Cholesterol metabolism is closely related to T cell function, and acyl-CoA: cholesterol acyltransferase 1 (ACAT1) inhibitors improve the anti-tumor function of CD8+ T cells by inhibiting cholesterol esterification in these cells." (PMID 40491907, 2025). "Targeting ACAT1 in tumor cells reduced mitochondrial hypersuccinylation and oxidative stress, enhancing TLS abundance and improving the efficacy of ICIs in preclinical murine models of NSCLC." (PMID 40166937, 2025). "The overexpression of ACAT1 further exacerbates cholesterol accumulation within tumor cells, contributing to tumor progression." (PMID 40391753, 2025). "In an animal study, a cancer stem cell antigens-loaded DC (CSCs-DC) vaccine was combined with an ACAT1 inhibitor to test the improvement of this treatment for HNSCC tumor recurrence and post-operative metastasis." (PMID 40491907, 2025). "To confirm the novel capacity of ACAT1 in antitumor immunity, we knocked out endogenous Acat1 in CT26 (MSS-CRC) cells and restored Acat1 expression with Acat1-Flag to examine tumor growth in BALB/c mice and NOD-scid IL2Rgnull (NSG) mice." (PMID 40289129, 2025). "Here, we showed that ACAT1 was more abundant in cell nuclei in peritumoral tissues than in tumor tissues." (PMID 40289129, 2025). "ACAT1 has also been found to be involved in tumour progression in a variety of cancer types most likely due to their reliance on cholesterol for membrane biogenesis and various biological processes." (PMID 41420301, 2025). "In conclusion, we confirmed that ACAT1 improved activated NK cells infiltration to restrict tumor growth." (PMID 40289129, 2025). "This action leads to a shift that promotes spontaneous formation of the tetramer, finally increasing ACAT1 activity and promoting the Warburg effect and tumor growth." (PMID 39494339, 2024). "Inhibition of the cholesterol esterifying enzyme ACAT1 has been shown to promote the anti-tumor effect of CD8 + T cells by facilitating the clustering of T cell receptors." (PMID 38627815, 2024). "Consistently, FFA accumulated in tumor tissues in the ACAT1 KD group, and the level of AcCoA was lower in the ACAT1 KD group than that in the vector group." (PMID 39494339, 2024). "We found that lower ACAT1 expression was correlated with higher individual stage, tumor grade, and nodal metastasis status." (PMID 39247186, 2024). "Avasimibe, a well-studied inhibitor of cholesterol esterification, has been found to effectively suppress tumor cell proliferation by targeting ACAT1 (SOAT1) to inhibit CE production." (PMID 38617549, 2024). "Clinical trials should be accelerated to evaluate the anti-tumor effects of more ACAT1 inhibitors in different cancer types." (PMID 38720812, 2024). "Univariate Cox survival analyses, in conjunction with Kaplan-Meier survival analysis of ACAT1, utilized data from 33 tumor types obtained from the TCGA database." (PMID 38817856, 2024). "The anti-tumor effect of ACAT1 inhibitors should be further verified in more cancer types in vitro and vivo models to explore the cancer types that can be effectively treated with ACAT1 inhibitors." (PMID 38720812, 2024). "The alterations of ACAT1 and ACSL3 are closely linked to the immune tumor microenvironment and progression of LUAD." (PMID 39323079, 2024). "Bitter melon extract has been reported to inhibit tumor cell growth in TNBC by downregulating ACAT1 expression." (PMID 38617549, 2024). "We also showed that silencing of ACAT1 expression in GBM cells led to inhibition of tumor proliferation in vivo and in vitro." (PMID 39494339, 2024). "While ACAT2 has limited value in cancers, ACAT1 has been found to be widely participated in tumor initiation and progression." (PMID 38720812, 2024).
tumor (continued). "IHC and H&E staining revealed decreased Ki67 expression in tumor tissues from patients with stable ACAT1 knockdown." (PMID 38817856, 2024). "We also examined the effects of increased ACAT1 expression on tumor growth in vivo using a xenograft mouse model." (PMID 39247186, 2024). "Inhibition of ACAT1 promoted the differentiation of GBM cells into astrocytes but also delayed tumor growth." (PMID 39494339, 2024). "Our data demonstrated a novel CAR-T cell type with silencing of the ACAT1 gene had stronger anti-tumor efficacy compared to conventional CAR-T cells." (PMID 38534399, 2024). "Taken together, the results of our study reveal that ACAT1 is an oncogenic driver in BLCA that enhances tumor proliferation and metastasis, indicating its potential as a diagnostic and therapeutic target for this disease." (PMID 38817856, 2024). "The findings affirmed that ACSL3 and ACAT1 expressions were upregulated and downregulated, correspondingly in tumor tissues." (PMID 39323079, 2024). "Further validation through the HPA database, focusing on both normal and KIRC tissue microarrays, affirmed this trend, illustrating an overall lower expression level of ACAT1 protein in KIRC tumor tissues compared to their normal tissues." (PMID 38297313, 2024). "ACAT1 is widely expressed in multiple tumor types, while ACAT2 is predominantly distributed in some organs, like small intestine and liver." (PMID 38213102, 2024). "qRT‐PCR results implied that ACSL3 and ACAT1 expressions were upregulated and downregulated, correspondingly in tumor tissues." (PMID 39323079, 2024). "Intriguingly, in contrast to the previous findings, ACAT1 inhibition has been shown to enhance the anti-tumor effect of CD8+ T cells by increasing free cholesterol in the cytoplasm, which promotes membrane synthesis." (PMID 37700339, 2023). "We then evaluated the ACAT1 expression in adjacent pre-tumour tissues and looked for possible differences with OSCC tumour tissue." (PMID 36816175, 2023). "In this context, pharmacological and genetic inhibition of ACAT1 (microsomal enzyme acetyl-coenzyme A-acetyl transferase 1) has been proven to attenuate tumor growth." (PMID 38299096, 2023). "Overall, these results indicate that fasting promotes cholesterol efflux via ABCG1 and possibly also via reduced ACAT1 expression, at least in some types of tumour cells." (PMID 37907500, 2023). "In tumor cells, however, ACAT1 is "hijacked" to regulate pyruvate dehydrogenase complex (PDC) and support the Warburg effect in human cancer." (PMID 36829161, 2023). "High expression of ACAT1 is related to cell proliferation rates, tumor formation and metastasis, and cell resistance." (PMID 37089950, 2023). "The accumulation of CE can be converted by tumor cells into cholesterol utilization, as demonstrated by high expression of ACAT1 and cholesterol ester metabolizing enzyme lysosomal acid lipase (LAL) in tumor tissues." (PMID 37089950, 2023). "The anti-tumor effectiveness can be increased by combining ACAT1 inhibitor and anti-PD-1 antibody therapy." (PMID 36677919, 2023). "We also demonstrated fasting to upregulate the cholesterol trasporter ABCG1 in tumours and to also downregulate ACAT1 in the HCT116 xenografts." (PMID 37907500, 2023). "The results from IHC performed on 61 OSCC tissues using ACAT1 antibody showed that ACAT1 is variably expressed among OSCC tumours, with high ACAT1 protein expression in 23 of 61 patients (37.7%) and low ACAT1 protein expression in 38 of 61 patients (62.3%)." (PMID 36816175, 2023). "ACAT1 is recognized as a tumor suppressor and is involved in several mitochondrial-induced metabolic pathways." (PMID 36902617, 2023). "As far as the TNM classification is concerned there was also a higher expression of HMGCR and ACAT1 mRNA in the tumoral region in comparison to the control region, especially in Stage II for both genes and Stage IV tumor tissue for ACAT1." (PMID 37024569, 2023).
tumor (continued). "This study aimed to investigate the expression level of ACAT1 between OSCC and the adjacent pre-tumour tissues and its association with the survival of OSCC patients." (PMID 36816175, 2023). "Both autophagy and increased ROS levels have certain tumor-inhibiting effects, and ACAT1 inhibits autophagy and eliminates intracellular ROS mainly by binding to FUS." (PMID 36517760, 2022). "We demonstrated the prognostic relevance of ACAT1 and CE in tumor tissue and peritoneal fluid of EOC patients." (PMID 35399074, 2022). "Among them, ACAT1 can promote epithelial mesenchymal transition of tumour cells and sensitivity to chemotherapeutic drugs." (PMID 36147503, 2022). "Further comprehensive prospective studies using large sample cohorts are needed to assess the correlation of plasma, peritoneal fluid and tumor ACAT1 with clinical and pathological features of patients." (PMID 35399074, 2022). "IHC analysis confirmed increased expression of ACAT1 protein in tumor tissue from the EOC group (evidenced by increased DAB staining) compared to normal or BPM tissues." (PMID 35399074, 2022). "Many studies assessed ACAT1 protein expression in tumor tissues primarily by IHC; however, we comprehensively measured ACAT1 expression at both the protein and mRNA levels utilizing ELISA, IHC and qRT-PCR." (PMID 35399074, 2022). "At the same time, ACAT1 inhibitor avamoib combined with anti-PD-1 immunotherapy can significantly improve the survival rate of tumor-bearing mice." (PMID 35444235, 2022). "Here, we systematically analyzed ACAT1 expression and CE levels in peritoneal fluid, plasma and tumor tissue in EOC patients and compared these to samples collected from patients with normal ovaries and/or benign pelvic masses." (PMID 35399074, 2022). "Through tumorigenic experiments in nude mice, we learned that the PC3 cell line with high expression of ACAT1 had tumorigenic properties, and the tumor weight was high (P = 0.0206)." (PMID 36517760, 2022). "The application of ACAT1, avasimibe (a small molecule inhibitor), in combination with a PD-1 inhibitor showed synergistic effects, significantly inhibiting the growth of tumor-bearing mice." (PMID 36046791, 2022). "Consistent with mRNA expression, ACAT1 protein levels were significantly higher (p < 0.001) in tumor tissue of women with EOC (n = 14) than those in samples collected from the non-malignant group (n = 19)." (PMID 35399074, 2022). "Previous studies show that ACADM and ACAT1 are protective tumor suppressors of KIRC, which is consistent with our findings." (PMID 36059510, 2022). "Combination therapy with an ACAT1 inhibitor and anti-PD-1 antibody showed better efficacy than immunotherapy alone in controlling tumor progression." (PMID 36059510, 2022). "ACAT1 is involved in maintaining appropriate levels of CE in non-tumor cells to support membrane stability." (PMID 35399074, 2022). "ACAT1 inhibition and CE depletion have anti-tumor effects, as measured by apoptosis regulation, cisplatin sensitivity, and cell proliferation, migration and invasion." (PMID 35399074, 2022). "QRT-PCR analysis showed that ACAT1 mRNA levels were significantly higher (p < 0.001) in the tumor tissue of women with EOC (n = 14) versus those measured in ovarian tissue from the combined non-malignant group (n = 11)." (PMID 35399074, 2022). "Commanding cholesterol esterification by the decreasing enzyme ACAT1 maintains the cholesterol level in the plasma membrane to potentiate T-cell anti-tumor responses." (PMID 36231064, 2022). "To further evaluate the suppressive effect of ACAT1 expression on NPC tumor cell growth, we compared the tumorigenesis of ACAT1-5-8F and ACAT1-HONE1 to that of the respective pCMV6-Entry control clones of 5-8F and HONE1 in vivo." (PMID 34485115, 2021). "For the cytotoxic T cells, tumor‐derived T cells showed stronger cholesterol homeostasis activities and significantly higher expression levels of ACAT1, a key cholesterol esterification enzyme." (PMID 33463049, 2021).